ZEB1 (zinc finger E-box binding homeobox 1)
Diseases named in the same sentence as ZEB1 in open-access papers (continued):
Sharing a sentence is not in itself a finding about the gene and the disease.
cervical carcinoma (continued). "After silencing ZEB1 in hypoxic cervical cancer cells, the recruitment of macrophages was decreased, and overexpression of ZEB1 in normoxic cervical cancer cells increased macrophage migration (all P < 0.05)." (PMID 31263103, 2019). "MiR-126 has the tumor suppressive effect, which suppresses the proliferation, migration and invasion in cervical cancer cells via targeting ZEB1." (PMID 31007650, 2019). "Hypoxia increased ZEB1 expression in cervical cancer cells, directly promoting CCL8 production and attracting macrophages via the CCR2–NF-κB pathway." (PMID 31263103, 2019). "This study showed that high ZEB1 expression in hypoxic cervical cancer cell islets was positively correlated with CD163+ TAM accumulation." (PMID 31263103, 2019). "The results suggest that the expression of miR-23b is regulated by the methylation of its promoter and is possible that this microRNA influence the expression of uPa, c-Met and Zeb1 in cervical cancer cells lines." (PMID 26622315, 2015). "More detailed studies are needed to determine if uPa, c-Met and Zeb1 are genes regulated by miR-23b in cervical cancer." (PMID 26622315, 2015). "LncRNA PCAT6 influences chemoresistance in cervical cancer by targeting the miR-543/ZEB1 axis." (PMID 38950346, 2024). "It has been demonstrated that hypoxia induces the binding of HIF-1α to the proximal promoter of zinc finger E-box binding homeobox 1 (ZEB1), which is highly expressed in cervical cancer hypoxic cells islets and is associated with a stronger pro-tumor phenotype." (PMID 38397187, 2024). "The silencing of ESM1 expression may inhibit the proliferation, invasion, metastasis and epithelial-mesenchymal transformation of cervical cancer cells by inhibiting ZEB1/PI3K/AKT." (PMID 38954708, 2024). "High ZEB1 expression accelerated cervical cancer progression through CCL8-induced TAMs recruitment." (PMID 36841801, 2023). "Thus, the CRNDE/miR-4262/ZEB1 signaling axis accelerates cervical cancer progression by increasing cell survival, EMT, migration, and invasion." (PMID 35774512, 2022). "In cervical cancer, miR-211 can inhibit cancer by inhibiting the expression of ZEB1." (PMID 35582235, 2022). "In addition, hypoxia in cervical cancer cells increases the expression of Zinc finger E-box binding homeobox 1 (ZEB1), which directly upregulates the production of CCL8 and then recruits macrophages." (PMID 35281057, 2022). "The EMT activator ZEB1 could regulate miR-203 expression, therefore, to maintain stem properties of cervical cancer cells." (PMID 34539782, 2021). "Similarly, Twist1 and Zeb1 were downregulated by increasing promoter methylation in cervical cancer CaSki and SiHa cell lines." (PMID 33923474, 2021). "Moreover, Snail was a superior prognosis factor compared to Slug, ZEB1, Twist, Vimentin, and Survivin in cervical carcinoma." (PMID 32185181, 2020). "SPRY4-IT1 also promoted EMT of cervical cancer cells via regulating miR-101-3p/ZEB1 axis." (PMID 33029299, 2020). "In addition, CCL8 upregulation was detected in ZEB1-transduced normoxic cervical cancer cell CM, and CCL8 was decreased in ZEB1-silenced hypoxic cervical cancer cell CM, suggesting that ZEB1 controls CCL8 production in cancer cells." (PMID 31263103, 2019). "In the current study, upregulated expression of ZEB1 was found in cervical cancer tissues." (PMID 31007650, 2019). "Moreover, the higher expression of ZEB1 in cervical cancer is positively correlated with advanced FIGO stage and LN metastasis." (PMID 31263103, 2019). "A poor prognosis was found in cervical cancer patients with high expression of ZEB1 and CCL8." (PMID 31263103, 2019). "Targeting EMT-TFs like Twist1 and Zeb1 might be the possible mechanism of action of TQ in controlling metastasis in cervical cancer." (PMID 29207526, 2017). "Moreover, Zeb1 has also been found as a new target for TQ potential therapy in cervical cancer cells." (PMID 29207526, 2017).
cervical carcinoma (continued). "Similarly, the silencing of FTO could suppress the proliferation and/or invasion of cervical cancer cells via the m6A modification of the myelocytomatosis oncogene (Myc) and the zinc finger E-box-binding homeobox 1 (ZEB1)." (PMID 37606395, 2023). "The results suggest that ZEB1 could directly target the CCL8 promoter in cervical cancer cells." (PMID 31263103, 2019). "Our study first uncovered that in the hypoxic TME, CCL8 from hypoxia-induced ZEB1-driven cancer cells induced macrophage infiltration mainly into the hypoxic area via the CCR2–NF-κB pathway, and this effect was associated with poor prognosis in cervical cancer." (PMID 31263103, 2019). "For example, in cervical cancer, FTO regulates m6A methylation of ZEB1 and Myc, key oncogenes involved in cell proliferation and migration." (PMID 41141648, 2025). "“miR-484 suppresses proliferation and epithelial-mesenchymal transition by targeting ZEB1 and SMAD2 in cervical cancer cells” published in Cancer cell international was retracted as a result of concerns/issues about data and duplication of image." (PMID 38984306, 2024). "Aloe-emodin is a potential treatment for cervical cancer, which can play an anti-tumor role by inhibiting ESM1/ZEB1." (PMID 38954708, 2024). "As ZEB1 was a transcription factor, we think this pathway should play a key role, and it will be a strong complement to the knowledge of ESM1 in regulating cervical cancer except angiogenesis pathway and PI3K-Akt/EMT pathway." (PMID 38954708, 2024). "MiR‐525‐5p was reported to inhibit cervical cancer metastasis through blocking the UBE2C and ZEB1/2 signaling pathway." (PMID 36705418, 2023). "Hsa-miR-200a has been shown to downregulate metastatic genes such as ZEB1, and ZEB2, which is suggested to suppress the migration of cervical cancer cells." (PMID 36879084, 2023). "A PPIN of 90 genes identified FLT1, IGF2, IRS1, JUN, KDR, ZEB1, TIMP2 (downregulated), and EZH2, SOX2, and MYB (upregulated) in cervical cancer samples when compared with normal samples." (PMID 36879084, 2023). "A crosstalk has been reported between ZEB1 and PTTG1, involving miR-3666 in cervical cancer cell lines." (PMID 36230799, 2022). "As reported by a previous literature, miR-525-5p was verified to be a tumor suppressor in cervical cancer via hampering epithelial-to-mesenchymal transition and anoikis resistance through UBE2C/ZEB1/2 signaling pathway." (PMID 34507559, 2021). "The targeting of ZEB1 and SMAD2 by miR-484 was predicted in our analysis and is reported to suppress proliferation and epithelial-mesenchymal transition in cervical cancer." (PMID 34547721, 2021). "Earlier it has been demonstrated that tumor suppressor miR-484 modulates the ZEB1 and SMAD222 and WNT/ MAPK pathway by directly targeting HNF1α in cervical cancer cells." (PMID 33214606, 2020). "Increased CAIX intensity, upregulated ZEB1 expression level, and increased number of CD63+ TAMs were strongly correlated with an advanced FIGO stage and lymph node (LN) metastasis of cervical cancer (all P < 0.05)." (PMID 31263103, 2019). "We conclude that TQ inhibits the migration and invasion of cervical cancer cells, probably via Twist1/E-Cadherin/EMT or/and Zeb1/E-Cadherin/EMT, among other signaling pathways." (PMID 29207526, 2017). "The results showed that aloe-emodin could effectively inhibit the proliferation, invasion of cervical cancer, further results demonstrated that aloe-emodin inhibited the ESM1/ZEB1/EMT axis." (PMID 38954708, 2024). "miR-203 can also regulate other targets in cervical cancer, including VEGF and ZEB1." (PMID 38789663, 2024). "Interestingly, TCGA data showed that both ZEB1 and CCL8 overexpression correlate with poor prognosis in human cervical cancer." (PMID 38397187, 2024). "Inhibitory effect of aloe emodin on ESM1/ZEB1/EMT signaling pathway and cervical cancer cells." (PMID 38954708, 2024).
cervical carcinoma (continued). "Given that we showed that APE1 inhibits EMT by inhibiting E-cadherin expression in cervical cancer cells, we next investigated whether APE1 is involved in ZEB1-regulated inhibition of E-cadherin expression." (PMID 34210327, 2021). "In addition, it was found that, based on the data analysis of the Cancer Genome Atlas (TCGA), ZEB1 and CCL8 are independent prognostic factors in cervical cancer patients." (PMID 34833360, 2021). "The levels of Slug, Twist, and ZEB1 expression between tumor tissues and normal tissues were not significant, and multivariate analysis demonstrated that Slug, Twist, ZEB1 were not independent prognostic factors in cervical carcinoma." (PMID 32185181, 2020). "Furthermore, ZEB1 and CCL8 were independent prognostic factors in cervical cancer patients based on The Cancer Genome Atlas (TCGA) data analysis." (PMID 31263103, 2019). "Thus, the results of our study linked to previous studies indicating that TQ inhibits the migration and invasion of cervical cancer cells probably via Twist1/E-Cadherin/EMT or/and different Zeb1/E-Cadherin/EMT signaling pathways." (PMID 29207526, 2017). "Although zeb1 is a direct target of miR-23b in bladder cancer, there are no current studies that support this theory in cervical cancer." (PMID 26622315, 2015). "At present, whether ZEB1 and ZEB2 involved in the cervical cancers remained to be explored in further details." (PMID 25197668, 2014). "Previous study identified miR‐484 as an inhibitor of cell proliferation and invasion by targeting ZEB1 and SMAD2 in cervical cancer cells, revealing that ZFAS1 may promote cell proliferation and invasion via sponging miR‐484 to modulate the expression of ZEB1 and SMAD2." (PMID 30288832, 2019). "Additionally, bta-miR-484 has been observed to prevent cell proliferation and epithelial–mesenchymal transition process by targeting both ZEB1 and SMAD2 genes, thus functions like a tumor suppressor and may serve as a prospective biomarker for cervical cancer." (PMID 30149509, 2018). "However we did not test effects of TQ on Zeb1 promoter methylation in cervical cancer cell lines due to the unavailability of this assay." (PMID 29207526, 2017). "In cervical cancer, several mechanisms are potentially involved in EMT induction, including epigenetic factors, low dose radiation, HPV oncogenes E6 and E7 and TGF-β expression, through transcription factors twist, ZEB1, snail/slug, and several matrix metalloproteinases." (PMID 29152102, 2017).
glioblastoma (72 papers, 2013 to 2025). The most malignant astrocytic tumor (WHO grade IV). "The CRISPR/Cas9-mediated KO and pharmacologic targeting of ZEB1 with honokiol reversed the mesenchymal gene expression and associated stem cell, invasion and metabolic changes of glioblastoma cells." (PMID 38139138, 2023). "It is our opinion that this is consistent with our account of ZEB1 deletion of which we see a frequency of 50% loss of ZEB1 in glioblastoma patients which corresponds to a shorter patient survival." (PMID 30705664, 2018). "The respective explanations for these outcomes are that ZEB1 loss results in the increase of stemness of the glioblastoma whereas the IDH1R132MUT results in inactivation of IDH1 from the use of isocitrate as a metabolic substrate." (PMID 30705664, 2018). "Downregulation of the steady-state levels of Nestin and ZEB1 was observed supporting that AMG232 modulates stemness regulators linked to maintenance of the glioblastoma 3D growth." (PMID 30022047, 2018). "Adding to the complexity of ZEB1 we previously demonstrated that the loss of ZEB1 imparts “stemness” to cancer stem cells derived from glioblastoma to prevent differentiation and induce self-renewal." (PMID 30705664, 2018). "Our patient population analyzing glioblastomas was significantly larger with >200 patients compared to >20 patients with ZEB1 loss or decreased expression." (PMID 30705664, 2018). "Comparing the whole of chromosome 10 and the specific ZEB1 locus in glioblastoma patients indicated significant copy number loss (respectively) relative to patient blood with normal copy number." (PMID 28246407, 2017). "With our focus on glioblastoma, we show high intra- und interindividual variation of the ZEB1 labeling index and an association with EGFR amplification and IDH mutation, i.e. molecular traits of the classical and proneural subtypes, respectively." (PMID 28945795, 2017). "Of note, we have previously identified a more quiescent population of glioblastoma stem cells, and we observed here that increased levels of ZEB1 are associated with slower proliferation." (PMID 23818228, 2013). "Based on our observation of reduced membrane-associated N-cadherin in invasive glioblastoma cells, we speculated that reduced cell–cell contacts contribute to greater invasiveness of ZEB1-positive cells." (PMID 23818228, 2013). "Recently, it was shown that chelerythrine reduces the protein expression of p-ERK1/2 and p-Smad2/3 and inhibits the TGF-β1-ERK1/2/Smad2/3-Snail/ZEB1 signaling pathway, thereby decreasing glioblastoma progression in U251 and T98G cell lines." (PMID 40286187, 2025). "Another recent study revealed that IL‐24 administration increased the expression of the epithelial marker E‐Cadherin and suppressed Zeb1 in glioblastoma multiforme (GBM) cell lines, leading to increased sensitivity to temozolomide." (PMID 40338095, 2025). "EMT-like markers and pathways, including Snail, ZEB1/2, Twist, and Wnt/TGF-β signaling, have been widely detected in glioblastoma and are implicated in tumor progression." (PMID 41018072, 2025). "IL-24 destabilized the stability of ZEB1 via increasing the expression of FBXO45 in human glioblastoma cells, contributing to inhibition of malignancy of glioblastoma." (PMID 38773471, 2024). "Their research demonstrated that CHE effectively suppresses the TGFB1-ERK1/2/Smad2/3-Snail/ZEB1 signaling pathway, thereby impeding the development of glioblastoma." (PMID 38675484, 2024). "For example, miR-590-3p reduced migration, invasion and EMT in glioblastoma multiforme by targeting ZEB1 and ZEB2, and in intrahepatic cholangiocarcinoma by targeting ZEB2." (PMID 37138218, 2023). "Transcription factor ZEB1 promotes glioblastoma tumor progression and is negatively correlated with the survival of patients with glioblastoma (Zeng, Xiao & Guo, 2019)." (PMID 35186504, 2022).
glioblastoma (continued). "In glioblastoma, MYB is an effector of the ZEB-1 pathway, which is implicated in epithelial–mesenchymal transition and key features of cancer stem cells." (PMID 33466745, 2021). "Recent studies showed that ZEB1 functions in embryonic neurogenesis, and we previously found that ZEB1 is crucial for the self-renewal of glioblastoma cancer stem cells." (PMID 34433050, 2021). "ZEB1 promotes cancer stemness in glioblastoma, where it is part of an autoregulatory loop together with SOX2 and OLIG2, two transcription factors with well-established functions in neural stem/progenitor cells." (PMID 34433050, 2021). "The influence of HIF-1α on ZEB1 was also evaluated among bladder cancer, glioblastoma and pancreatic cancer cells." (PMID 32322559, 2020). "For instance, overexpression of lncRNA SBF2-AS1 led to the promotion of temozolomide chemoresistance in glioblastoma cells and tissues via a ZEB1-dependent pathway." (PMID 32266287, 2020). "There is increasing evidence that high ZEB1 expression is also one of the significant indicators of poor prognosis in chemoresistant glioblastoma disease." (PMID 32266287, 2020). "In parallel, TGF-beta induces the mesenchymal phenotype in glioblastoma cells via pSmad2- and ZEB1-dependent signaling, leading to tumor invasion." (PMID 32266287, 2020). "ZEB1 is highly expressed in glioblastoma cells, where a ZEB1-miR200 feedback loop connects this with a number of downstream targets (ROBO1, c-MYB and MGMT), and increased levels of this EMT-TF are associated with both drug resistance and reduced survival." (PMID 32226927, 2020). "In glioblastoma cells, the ZEB1 pathway is closely related to tumor initiation, invasion, and chemoresistance." (PMID 32850368, 2020). "We found AMG232 suppresses Nestin and ZEB1 indicating the inhibitor leads to inhibition of the glioblastoma stemness." (PMID 30022047, 2018). "Further studies have attempted to delineate specific ZEB1 functions at the molecular level as the genes it regulates in glioblastoma as a tumor promoter remain poorly understood." (PMID 32309604, 2018). "In a heterogenous cancer such as glioblastoma it is possible that there are areas of high and low to null ZEB1 expression." (PMID 32309604, 2018). "LncRNA MALAT1 is up-regulated in multidrug-resistant glioblastoma cell lines and decreases the sensitivity of glioblastoma cells to TMZ by up-regulating EMT-related proteins (ZEB1, Snail and SLUG)." (PMID 29458374, 2018). "Silencing FGFR1 or FOXM1 downregulated genes involved in mesenchymal transition such as GLI2, TWIST1, and ZEB1 in glioblastoma stem-like cells." (PMID 30167084, 2018). "Knockdown of ZEB1 in three cell lines generated from primary glioblastoma specimens (hGBM L0, L1, and L2) inhibited invasion." (PMID 29165393, 2017). "In conclusion, our data support the notion of ZEB1 as universally expressed transcription factor in human glioblastoma with high inter- and intratumoral heterogeneity, which is best explained by differential contribution of the tumor microenvironment." (PMID 28945795, 2017). "To overcome the limitation of missing tumor markers for IDH-wildtype glioblastoma, we next analyzed a panel of nine patient-matched gliomasphere cell lines to further test differences in ZEB1 expression within a pure population of tumor cells." (PMID 28945795, 2017). "ZEB1 deletion and expression can be used to prognosticate glioblastoma patients with greater accuracy." (PMID 28246407, 2017). "We here provide a comprehensive characterization of ZEB1 in a large series of human glioblastoma with respect to clinical and molecular traits." (PMID 28945795, 2017). "ZEB1 expression in glioblastoma patients is predictive of shorter survival and poor temozolomide response." (PMID 25890268, 2015). "Analysis of the TCGA glioblastoma multiforme dataset found that ZEB1 expression also shows a statistically significant increase (p value<0.05) in samples with high EGFR amplification in this dataset." (PMID 25058589, 2014).